TRIP13 (thyroid hormone receptor interactor 13)
Description:
Plays a key role in chromosome recombination and chromosome structure development during meiosis. Required at early steps in meiotic recombination that leads to non-crossovers pathways. Also needed for efficient completion of homologous synapsis by influencing crossover distribution along the chromosomes affecting both crossovers and non-crossovers pathways. Also required for development of higher-order chromosome structures and is needed for synaptonemal-complex formation. In males, required for efficient synapsis of the sex chromosomes and for sex body formation. Promotes early steps of the DNA double-strand breaks (DSBs) repair process upstream of the assembly of RAD51 complexes. Required for depletion of HORMAD1 and HORMAD2 from synapsed chromosomes (By similarity). Plays a role in mitotic spindle assembly checkpoint (SAC) activation.
Synonyms: 16E1BP; MVA3; OOMD9; OZEMA9
Tractability: Small molecule: a structure with a bound ligand is known. PROTAC: ubiquitination databases record sites on it; its protein half-life has been measured.
Gene: Protein-coding gene on chromosome 5 (892,884 to 919,357, forward strand). Ensembl gene ENSG00000071539.
Subcellular location (Human Protein Atlas): Nuclear speckles; Nucleoplasm; Acrosome; Cytosol; Equatorial segment; Principal piece
Gene Ontology:
Molecular function: identical protein binding; protein binding; ATP binding; transcription coregulator activity; ATP hydrolysis activity
Biological process: mitotic spindle assembly checkpoint signaling; double-strand break repair; meiotic recombination checkpoint signaling; oogenesis; reciprocal meiotic recombination; spermatogenesis; synaptonemal complex assembly; transcription by RNA polymerase II
Cellular component: nucleus; male germ cell nucleus
Genetic constraint (gnomAD): Loss-of-function variants: 23 observed, 55.05 expected, observed/expected ratio (o/e) 0.42, 90% interval 0.3 to 0.59. The upper end of that interval is the gene's LOEUF score, 0.59, which puts it in group 2 of 6, group 1 being the genes least tolerant of losing a copy. Missense variants: 371 observed, 541.16 expected, observed/expected ratio (o/e) 0.69, 90% interval 0.63 to 0.75. Synonymous variants: 206 observed, 209.27 expected, observed/expected ratio (o/e) 0.98, 90% interval 0.88 to 1.11.
Homologues: Orthologues: macaque TRIP13 (99% identical), pig TRIP13 (94% identical), dog TRIP13 (93% identical), mouse Trip13 (93% identical), guinea pig TRIP13 (93% identical), rat Trip13 (85% identical), chimpanzee TRIP13 (82% identical), tropical clawed frog trip13 (79% identical), zebrafish trip13 (66% identical), Drosophila melanogaster pch2 (42% identical).
Diseases named in the same sentence as TRIP13 in open-access papers:
TRIP13 is named in the same sentence as 106 diseases in open-access papers, as found by Europe PMC text mining. Sharing a sentence is not in itself a finding about the gene and the disease. The quoted sentences say what the papers report.
colorectal cancer (27 papers, 2016 to 2025). A primary or metastatic malignant neoplasm that affects the colon or rectum. "TRIP13 overexpression is also associated with chemotherapy resistance, promotes the progression of head and neck cancer, breast cancer, and colorectal cancer, and is significantly associated with poor prognosis in patients." (PMID 41487520, 2025). "TRIP13, critical for the inactivation of the spindle assembly checkpoint, is associated with the progression of certain cancers, and was found to be highly expressed in multiple colorectal cancer tissues as assessed by RT-PCR." (PMID 29088818, 2017). "In colorectal cancer, high TRIP13 expression activated glycolysis, enhancing cell stemness and doxorubicin resistance." (PMID 41007830, 2025). "TRIP13 promotes the metastasis of colorectal cancer and its inhibition decreased cell proliferation in vitro and tumor formation in vivo of colorectal carcinoma cell lines." (PMID 39189258, 2024). "The small molecule inhibitor DCZ0415 targeting TRIP13 has been reported to restrain the multiplication ability of multiple myeloma cells, colorectal cancer cells, pancreatic ductal adenocarcinoma cells, and lung adenocarcinoma cells." (PMID 39187490, 2024). "Recently, TRIP13 has been shown to interact with the Wnt pathway in colorectal cancer, where it is significantly more highly expressed in tumours than in adjacent normal tissue." (PMID 39184376, 2024). "Other studies looking at cancers such as glioblastoma, colorectal carcinoma, osteosarcoma, non-small cell lung cancer, and hepatocellular carcinoma have shown that increased TRIP13 expression led to increased proliferation, migration, and invasion." (PMID 38589567, 2024). "In colorectal cancer, aberrant expression of TRIP13 contributed markedly to the aggressive phenotype of cancer cells, and its overexpression induced the downregulation of miR-129-5p and miR-4693-5p." (PMID 38067275, 2023). "Our recent study and others have found that TRIP13 is upregulated in colorectal cancers (CRCs; 55–80%), promotes cancer cell growth, promotes disease progression and indicates poor patient survival." (PMID 35194944, 2022). "In the development of colorectal cancer, high mRNA level of TRIP13 can be observed from the early stage." (PMID 33237662, 2021). "An increase in the level of mRNA of TRIP13 can be observed in the development of colorectal cancer from an early stage." (PMID 33237662, 2021). "Recently, TRIP13 has been found to be overexpressed in various types of cancers, including colorectal cancer, lung adenocarcinoma, ovarian cancer, prostate cancer and head and neck cancer." (PMID 34066132, 2021). "Thyroid hormone Receptor Interactor 13 (TRIP13) was reported to be a prognostic biomarker for colorectal cancer and prostate cancer." (PMID 31739630, 2019). "On the other hand, the cancer type showing more results for TRIP13 overexpression was colorectal cancer, followed by lung and sarcoma." (PMID 26527623, 2016). "Furthermore, TRIP13 is markedly expressed in colorectal cancer and can trigger glycolysis to enhance cell stemness, thus increasing the resistance of colorectal cancer cells to doxorubicin." (PMID 41311582, 2025). "Despite recent studies on TRIP13 in the human head and neck, prostate, and colorectal cancers have suggested its involvement in drug resistance and carcinogenesis, the oncogenic function of TRIP13 in gastric malignancy remains largely unknown." (PMID 37432513, 2023). "TRIP13 is upregulated in patients with colorectal cancer (CRC)." (PMID 35194944, 2022). "TRIP13 strongly suggests that overexpression may be a common phenotype in colorectal cancer and a potential finding/biomarker for early stage colorectal cancer diagnosis." (PMID 33237662, 2021). "They suggest that TRIP13 is involved in colorectal cancer cell proliferation and invasion, and may be a potential indicator for colorectal cancer treatment." (PMID 33237662, 2021).
colorectal cancer (continued). "Furthermore, it establishes role of TRIP13 in colorectal cancer metastasis and identifies COL6A3, TREM2, SHC3, and KLK7 as its downstream targets." (PMID 33037736, 2020). "Overexpression of TRIP13, a member of the AAA‐ATPase family, is linked with various cancers, but its role in metastasis is unknown in colorectal cancer (CRC)." (PMID 33037736, 2020). "Recent findings suggested that TRIP13 is overexpressed in and can promote tumorigenesis of several cancers, such as lung adenocarcinoma, chronic lymphocytic leukemia, head and neck cancer and colorectal cancer." (PMID 30386706, 2018). "In colorectal carcinoma (CRC), TRIP13 interacted with the receptor tyrosine kinase fibroblast growth factor receptor 4 (FGFR4) and activated the epidermal growth factor receptor (EGFR)/AKT pathway to induce EMT." (PMID 36268276, 2022). "TRIP13 might also be a potential target for the treatment of colorectal cancer." (PMID 32903581, 2020). "Thyroid receptor‐interacting protein 13 (TRIP13), a protein of the AAA‐ATPase family, is upregulated in various human cancers, including colorectal cancer (CRC)." (PMID 35194944, 2022). "The real-time RT-PCR technique was recently applied to measure expression levels of CPEB4, APC, TRIP13, EIF2S3, EIF4A1, IFNg, PIK3CA, and CTNNB1 genes in tumors and peripheral blood samples of colorectal cancer patients in stages I–IV of the disease." (PMID 36553654, 2022). "The mRNA levels of CPEB4, APC, TRIP13, EIF2S3, EIF4A1, IFNg, PIK3CA and CTNNB1 genes expressed in colorectal cancer tissue specimens, colorectal cancer blood samples, normal colon tissues and blood samples were analysed." (PMID 33237662, 2021). "The aim of the study is to assess expression levels of CPEB4, APC, TRIP13, EIF2S3, EIF4A1, IFNg, PIK3CA and CTNNB1 genes in tumors and peripheral bloods of colorectal cancer patients in stages I–IV." (PMID 33237662, 2021). "For GPAT3-TRIP13 gene pair, both up-regulation of TRIP13 and down-regulation of GPAT3 contribute to the reversal REO in colorectal cancer samples." (PMID 29378509, 2018). "TRIP13 expression also rises from colorectal adenoma to carcinoma, and its overexpression in colorectal cancers is independent of multiple patient factors." (PMID 41007830, 2025). "The study concluded that TRIP13 and CPEB4 mRNA up-regulation in the peripheral blood of patients with colorectal cancer might be a potential target for an early-stage test of colorectal cancer." (PMID 36553654, 2022). "The results reported in this study appears to suggest that the increase in TRIP13 and CPEB4 mRNA levels in peripheral blood samples of colorectal cancer cases may be a potential biomarker in early stage diagnosis of colorectal cancer." (PMID 33237662, 2021). "TRIP13 and CPEB4 mRNA up regulation in the peripheral blood of patients with colorectal cancer may be a potential target for early stage diagnosis." (PMID 33237662, 2021).
breast carcinoma (22 papers, 2008 to 2025). "TRIP13 is a novel mitotic checkpoint-silencing protein, whose overexpression is associated with poor prognosis in breast cancer patients." (PMID 29378509, 2018). "High expression of TRIP13 gene was reported to be associated with poor prognosis in breast cancer." (PMID 27609023, 2016). "Functionally, TRIP13 promotes breast cancer cell proliferation and migration, supporting its role as a driver of tumor progression and a potential diagnostic or therapeutic target." (PMID 41487520, 2025). "A previous study indicates that TRIP13 is elevated in Breast Cancer tissues, especially in lung metastatic lesions, and it can facilitate the proliferative and migratory abilities of BC cells." (PMID 38914609, 2024). "Since then, further research has highlighted the crucial role of TRIP13 in regulating tumor cell survival, expansion, and invasion across various cancer types, including colon, prostate, and breast cancer." (PMID 37740123, 2023). "In 1995, it was discovered that the TRIP13 protein, which interacts with the thyroid receptor in breast cancer cell lines, belongs to the AAA + ATPase superfamily." (PMID 37740123, 2023). "More recently, miR-30c-1-3p and miR-30c-2-3p were found to be significantly downregulated in breast cancer (BrCa) tissues, and their target gene TRIP13 was overexpressed in BrCa tissues." (PMID 38067275, 2023). "In order to access the potential for TRIP13 to be used in the diagnosis of breast cancer, receiver operating characteristic (ROC) curve analysis was performed and area under the curve (AUC) values were calculated." (PMID 35322916, 2022). "In order to ascertain the role of TRIP13 in BC, an animal model of breast cancer was established, with histological diagnosis of primary tumour and lung metastatic lesion conducted using HE staining." (PMID 35322916, 2022). "In previous study, a total of 21 proteomic signatures regulated by HMGA1 in breast cancer were reported, and three of them (KIFC1, LRRC59, and TRIP13) were verified to promote breast cancer progression." (PMID 33648560, 2021). "Thyroid hormone receptor interacting protein 13 (TRIP13) is upregulated in some cancers including breast cancer." (PMID 27876705, 2016). "As GSEA predicted that TRIP13 may facilitate breast cancer progression through PI3K‐AKT‐mTOR signalling pathways." (PMID 35322916, 2022). "Next, we also studied the effect of Trip13 KD in SK‐BR3 human breast cancer cells." (PMID 36031387, 2022). "TRIP13 is an onco-protein in several types of cancers and is abnormally expressed in various human tumors, including head and neck cancer, hepatocellular carcinoma, colorectal cancer, breast cancer, etc.." (PMID 33648560, 2021). "High TRIP13 expression has been identified in multiple cancers, including prostate cancer, primary cutaneous T-cell lymphoma, non-small cell lung cancer, and breast cancer." (PMID 28157697, 2017). "By interrogating a breast cancer gene expression data set (GOBO data set), we obtained the expression of KIFC1, LRRC59, and TRIP13 genes for tumor samples stratified according to HU and PAM50 subtypes, ER status, and histological grade." (PMID 26527623, 2016). "However, the function of TRIP13 in breast cancer (BC) has not yet been elucidated." (PMID 35322916, 2022).
hepatocellular carcinoma (22 papers, 2016 to 2025). A malignant tumor that arises from hepatocytes. "In hepatocellular carcinoma, high TRIP13 expression correlates with increased Th2 cell infiltration and reduced infiltration of neutrophils, Th17 cells, and dendritic cells." (PMID 41007830, 2025). "Diminished Trip13 levels in hepatocellular carcinoma cells result in insulin‐receptor‐/Akt‐pathway‐dependent accumulation of lipid droplets, which act as functional acentriolar microtubule organizing centers disturbing mitotic spindle polarity." (PMID 36031387, 2022). "In hepatocellular carcinoma and bladder cancer cells, TRIP13 knockdown induced the increase of E-cadherin and the decreases of N-cadherin and Snail, suggesting that TRIP13 promotes metastasis via inducing the EMT." (PMID 35075117, 2022). "In hepatocellular carcinoma, TRIP13 regulated by miR-192-5p was shown to interact with and increase the expression of actinin alpha 4 (ACTN4), thus activating the AKT/mammalian target of rapamycin (mTOR) pathway to drive tumor progression." (PMID 36268276, 2022). "Prior studies have implicated these TRIP13 targets in the progression of various cancers, including COL6A3 and KLK7 in CRCs, SHC3 in hepatocellular carcinomas, and TREM2 in gastric cancers and renal cell carcinomas." (PMID 33037736, 2020). "TRIP13 inhibition may be useful in treating diverse cancer types, including hepatocellular carcinoma (HCC), myeloma, colon cancer, chronic lymphocytic leukemia (CLL), bladder cancer, head and neck squamous cell carcinoma (HNSCC), non-small cell lung cancer (NSCLC), and prostate cancer." (PMID 40228580, 2025). "Our study now discovers a new role of Trip13 in metabolic reprograming in hepatocellular carcinoma (HCC)." (PMID 36031387, 2022). "In order to explore the effect of silencing TRIP13 on tumorigenecity of Hepatocellular carcinoma, 9 nude mice were transplanted with HepG2 cells to establish HCC models in vivo." (PMID 30564064, 2018). "Several scientists pointed out that CDC20, CEP55, TRIP13, MYBL2 were overexpressed in hepatocellular carcinoma, compared with adjacent normal tissues." (PMID 38297250, 2024). "In hepatocellular carcinoma (HCC), upregulated TRIP13 induced malignant transformation of HCC in vitro and lung metastasis in vivo." (PMID 38067275, 2023). "In hepatocellular carcinoma (HCC) cells, TRIP13 knockdown increases levels of the epithelial marker, E‐cadherin, and decreases the mesenchymal markers, vimentin, and snail." (PMID 33037736, 2020). "In addition, the ACTN4 and TRIP13 complex promotes EMT and tumor metastasis through the Akt signaling in hepatocellular carcinoma cells." (PMID 33363146, 2020). "For example, TRIP13 plays an oncogenic role in glioblastoma via the FBXW7/c-MYC pathway and induces hepatocellular carcinoma (HCC) cell migration, invasion, and metastasis through AKT/mTOR signaling via and interaction with ACTN4." (PMID 38012658, 2023). "This study explores the function of TRIP13 and synergistic effects of TRIP13 and PARP1 inhibitors in hepatocellular carcinoma (HCC)." (PMID 35517402, 2022). "A recent study demonstrated that the TRIP13 inhibitor DCZ0415 impairs nonhomologous end-joining repair and attenuates cancer cell growth in hepatocellular carcinoma." (PMID 37627217, 2023). "The deletion of TRIP13 may damage the repair process of nonhomologous end joining A (NHEJ) in hepatocellular carcinoma A (HCC)." (PMID 33294448, 2020).